VHL (von Hippel-Lindau tumor suppressor)
Diseases named in the same sentence as VHL in open-access papers (continued):
Sharing a sentence is not in itself a finding about the gene and the disease.
familial erythrocytosis (3 papers, 2021 to 2022). "A review of the literature on recently reported mutations in patients with non-MPN erythrocytosis, highlighted the role of some known genes associated with familial erythrocytosis, such as EPO, HBB, VHL EGLN1, EPAS1, and EPOR." (PMID 36290845, 2022). "VHL mediates tumour invasion and metastasis by regulating HIF protein expression, and VHL mutations predispose patients to several angiogenic tumours (familiar VHL tumour syndrome) and familial erythrocytosis 2 (ECYT2)." (PMID 36051068, 2022).
fibrosis (3 papers, 2012 to 2024). the formation of excess fibrous connective tissue in an organ or tissue in a reparative or reactive process. "The results showed that liver sections from fibrosis patients had a lower level of VHL and higher levels of HIF-1α and HIF-2α compared with healthy sections, a finding which was confirmed in mice." (PMID 28112200, 2017).
gastrointestinal stromal tumor (3 papers, 2016 to 2024). "In addition to VHL, which causes familial RCC, the mutation of SDH predisposes one to oncocytic RCC and gastrointestinal stromal tumors (GIST) with a lower frequency than paraganglioma and phenochromocytoma." (PMID 35326646, 2022).
head and neck cancer (3 papers, 2012 to 2022). A primary or metastatic malignant neoplasm affecting the head and neck. "Hypomethylation of VHL has been reported in head and neck cancer and lung squamous carcinoma." (PMID 29933410, 2018).
Hepatic steatosis (3 papers, 2012 to 2021). Steatosis is a term used to denote lipid accumulation within hepatocytes. "Additional insight into the potential role of HIFs in the pathogenesis of hepatic steatosis during IH has been obtained from mice with deficiency of Von Hippel-Lindau (VHL) tumor suppressive protein in the liver." (PMID 23087670, 2012). "VHL deletion in hepatocytes, which is preventing the proteasome degradation of HIFα subunits, resulted in the overexpression of both HIF1α and HIF2α and then in the rapid development of an impressive fatty liver associated with an impairment of fatty acid oxidation." (PMID 34359934, 2021). "VHL deficient mice have severe hepatic steatosis which was prevented by HIF-2α but not HIF-1α knockout suggesting that HIF-2 contributes to the pathogenesis of hepatic steatosis." (PMID 23087670, 2012). "However, applicability of findings in the VHL KO model to hepatic steatosis induced by IH is uncertain." (PMID 23087670, 2012).
ischemia (3 papers, 2011 to 2025). A hypoperfusion of the BLOOD through an organ or tissue caused by a PATHOLOGIC CONSTRICTION or obstruction of its BLOOD VESSELS, or an absence of BLOOD CIRCULATION. "Therefore, the cardiac oxygen-sensing VHL/HIF/EPO pathway may represent an endogenous cardioprotective response that works in tandem with other pathways (e.g. adenosine) to locally induce cardiomyocyte tolerance against ischemia or ischemia-reperfusion damage." (PMID 21811636, 2011). "Given the significance of the VHL-HIF-1α interaction in determining HIF-1α abundance, efforts have been made to develop small-molecule drugs targeting this interaction for the treatment of conditions like chronic anemia and ischemia." (PMID 40691138, 2025).
liver fibrosis (3 papers, 2017 to 2026). "In this study, we investigated the change of VHL expression during liver fibrosis and whether overexpression of VHL may have a therapeutic benefit to attenuate liver fibrosis and further illustrated the underlying mechanism." (PMID 28112200, 2017). "Overexpression of VHL attenuated liver fibrosis, downregulated fibrogenic genes, and inhibited liver inflammation, apoptosis, and angiogenesis." (PMID 28112200, 2017). "Normoxia-active HIF-1α or HIF-2α prevented the inhibitory effect of VHL on liver fibrosis, indicating that attenuating fibrosis via VHL is HIF-1α- and HIF-2α-dependent to some extent." (PMID 28112200, 2017). "We found VHL overexpression might be therapeutic in mouse models of established liver fibrosis, but it is also possible that it inhibits the progression of liver fibrosis in the last 1 or 2 weeks of the experimental models." (PMID 28112200, 2017). "To date, little is known about the change of VHL during liver fibrogenesis, whether regulation of VHL could inhibit the progress of liver fibrosis and contribute to the antifibrogenic potential of HSCs." (PMID 28112200, 2017). "Interestingly, when VHL and HIF-1α or HIF-2α were both overexpressed, HIF-1α and HIF-2α were equally effective at preventing the inhibitory effect of VHL on liver fibrosis, and the dominant effect of HIF-2α in toxic liver fibrosis did not exist." (PMID 28112200, 2017). "To determine whether VHL also decreased during liver fibrosis in mice, we used two models, BDL and long-term CCl4 injection." (PMID 28112200, 2017). "By targeting VEGF and pFGFR-1, VHL inhibited neovascularization in the liver during fibrosis, which might account for the effect of VHL on liver fibrosis." (PMID 28112200, 2017). "Furthermore, VHL overexpression attenuates liver fibrosis through a HIF-α-dependent pathway and inactivates HSCs both in vitro and in vivo." (PMID 28112200, 2017). "To extend our findings, we next tested whether VHL-mediated inhibition of liver fibrosis was HIF-1α- or HIF-2α-dependent." (PMID 28112200, 2017). "Altogether, our results suggest that VHL plays a crucial role in liver fibrosis." (PMID 28112200, 2017). "Because VHL inhibited liver fibrosis in vivo, we hypothesized that VHL overexpression could inhibit HSC activation." (PMID 28112200, 2017). "Taken together, VHL may be considered a new target to inhibit liver fibrosis." (PMID 28112200, 2017). "In addition, silencing HIF-1α plus HIF-2α was significantly weaker at inhibiting fibrosis compared with VHL overexpression, indicating that there may be an HIF-1α- and HIF-2α-independent pathway for VHL to attenuate liver fibrosis." (PMID 28112200, 2017). "Thus, VHL may be considered a new target to prevent the development and progression of liver fibrosis." (PMID 28112200, 2017). "The results showed that injection of Ad-VHL still led to reduced histological fibrosis in BDL- and CCl4-treated mice compared with injection of Ad-Null, which indicated that VHL overexpression can be therapeutic in mouse models of established liver fibrosis." (PMID 28112200, 2017).
medulloblastoma (3 papers, 2018 to 2024). A malignant, invasive embryonal neoplasm arising from the cerebellum. "Thus, our study is one of the first to connect VHL to REST-dependent control of autophagy in a subset of medulloblastomas." (PMID 38866867, 2024).
mesothelioma (3 papers, 2010 to 2024). A usually malignant and aggressive neoplasm of the mesothelium which is often associated with exposure to asbestos. "In a word, both primary ovarian mesothelioma and clear cell variant of mesothelioma with VHL mutations are extremely rare, and a careful diagnosis needs to be made by combining histomorphology, immunohistochemistry, and genetic testing." (PMID 39605894, 2024). "The immunohistochemical results of the patient were consistent with the diagnosis of mesothelioma, and the final diagnosis was ovarian mesothelioma (clear cell type) with VHL gene mutation." (PMID 39605894, 2024). "Through literature retrieval, a total of seven cases of mesothelioma with VHL gene mutations were reported, including six cases of peritoneal mesothelioma and one case of pleural mesothelioma, and no ovarian mesothelioma has been reported." (PMID 39605894, 2024). "VHL gene mutations have been previously shown in a proportion of cell lines derived from small-cell lung cancer, NSCLC, carcinoids, and mesotheliomas." (PMID 20461082, 2010).
neurocutaneous disorder (3 papers, 2017 to 2025). "Von Hippel-Lindau (VHL) disease is a rare neurocutaneous disorder characterized by multiple benign and malignant tumors involving different organs (renal, adrenal, pancreas, liver, urogenital system, central nervous system, and head and neck region) due to mutations in the VHL tumor suppressor gene." (PMID 37905285, 2023). "Given this expanding understanding, it becomes increasingly pertinent to examine the role of epigenetic dysregulation in neurocutaneous syndromes such as TSC, VHL and A-T." (PMID 40558831, 2025). "This comprehensive review underscores the critical role of epigenetic mechanisms in the pathogenesis, prognosis and management of neurocutaneous syndromes, with a focus on TSC, VHL, and A-T." (PMID 40558831, 2025). "VHL and TSC are two of the ~10 phakomatoses that are characterized by dominant inheritance and scattered heterozygous precancerous lesions." (PMID 27682873, 2017).
neuroendocrine pancreatic neoplasms (3 papers, 2021 to 2023). "In summary, pancreatic neuroendocrine neoplasms in the context of VHL have distinct characteristics compared with sporadic PNENs, including a lower rate of metastases and a lower grade, and are mostly non-functional neoplasms." (PMID 36980625, 2023).
neurofibromatosis (3 papers, 2016 to 2024). A hereditary neoplastic syndrome in which tumors grow in the nervous system. "Two nonsyndromic patients (cases 1 and 2) were negative to germline mutations in genes VHL, SDHB, SDHC, SDHD, SDHAF2, TMEM127, and MAX, while the third case (case 3) had clinical diagnosis of neurofibromatosis syndrome." (PMID 36187102, 2022).
non-small cell lung carcinoma (3 papers, 2006 to 2022). A group of at least three distinct histological types of lung cancer, including non-small cell squamous cell carcinoma, adenocarcinoma, and large cell carcinoma. "The enrichment of KRAS signaling upon VHL restoration is probably related to the paradoxical function of HIF2α to constrain KRAS-AKT signaling in non-small cell lung cancer driven by KrasG12D." (PMID 35159281, 2022). "More recently, we showed that both EGF and hypoxia can induce CXCR4 expression in non-small cell lung cancer (NSCLC) cells via the VHL/HIF-1α axis and this process is regulated by both the PI3-kinase/PTEN/AKT/mTor pathway and hypoxia." (PMID 17083723, 2006).
Obesity (3 papers, 2021 to 2026). Accumulation of substantial excess body fat. "Moreover, the associations of VHL somatic mutations and ccA/ccB subtypes with race and ethnicity changed after adjusting for behavioral factors, such as obesity and smoking, suggesting that these factors potentially affect molecular characteristics." (PMID 37081700, 2023).
pituitary adenomas (3 papers, 2015 to 2025). "Indeed, lesser expression of the native VHL protein in pituitary adenomas was found to highly associate with increased expression of the angiogenic VEGF protein and high rates of recurrence." (PMID 39939491, 2025). "Of note, most pituitary adenomas also stained positively with VHL with differing intensities and distributions, and the common localization of VHL protein in cell nuclei in poorly vascularized somatotroph adenomas was hypothetically linked to an inhibitory function of VHL in pituitary angiogenesis." (PMID 39939491, 2025). "Known pheo/PGL genes (SDHA-D, SDHAF2, RET, VHL, TMEM127, MAX, FH) and pituitary adenoma genes (MEN1, AIP, CDKN1B) were sequenced using next generation or Sanger sequencing." (PMID 25494863, 2015).
psoriasis (3 papers, 2015 to 2023). An autoimmune condition characterized by red, well-delineated plaques with silvery scales that are usually on the extensor surfaces and scalp. "In previous work, we found expression of the VHL gene in healthy skin, in contrast to the lesional skin of psoriasis patients, where its expression is almost absent." (PMID 35563616, 2022). "Perhaps in the psoriasis Treg cells treated with trichostatin-A occurred that when HDAC-1 was inhibited, the expression of VHL augmented, HIF-1α was proteolyzed, and the expression of IL-17 decreased, giving as result that Treg cells could not switch to Th17." (PMID 26136626, 2015).
squamous cell carcinoma (3 papers, 2011 to 2017). A carcinoma arising from squamous epithelial cells. "We describe a case of squamous cell carcinoma in the tongue caused by a point mutation in the splicing region of the VHL gene and discuss its association with VHL disease." (PMID 22462637, 2012). "Previously, we reported that the loss of heterozygosity (LOH) of the VHL gene is common in squamous cell carcinoma tissues of the tongue." (PMID 22462637, 2012). "In this report, we describe a splicing abnormality of the VHL gene in a patient with a squamous cell carcinoma (SCC) of the tongue." (PMID 22462637, 2012).
Stroke (3 papers, 2022 to 2025). Sudden impairment of blood flow to a part of the brain due to occlusion or rupture of an artery to the brain. "Among these, three are likely monogenic causes of stroke (ELN, SCN5A, and VHL genes), two are considered risk factors (FV and ADAMTS13), two have conflicting interpretations (ACAD9 and ENG), and three are most likely benign (CBS, PMM2, and PKD1)." (PMID 40650005, 2025). "Recently, attention has been focused on the role of HIF-1α in NSCs during nerve regeneration after traumatic brain injury and stroke; furthermore, VHL, upstream of HIF-1α, is thought to play an important role in this process." (PMID 36835292, 2023). "In addition, because SOCS and VHL promote nerve regeneration, they are expected to be applied in neuronal regenerative medicine for traumatic brain injury and stroke." (PMID 36835292, 2023). "In addition, because SOCS and VHL proteins promote nerve regeneration, they are expected to be applied in nerve-regenerative medicine for traumatic brain injury and stroke." (PMID 36835292, 2023).
thymoma (3 papers, 2019 to 2021). A neoplasm arising from the epithelial cells of the thymus. "A case was reported of an antibody-positive MG patient with thymoma concurrent with VHL." (PMID 34603387, 2021).
adenoma (2 papers, 2015 to 2017). A neoplasm arising from the epithelium. "Two patients had a VHL mutation, one with a PRL and one with a GH- and PRL-secreting adenoma." (PMID 25494863, 2015).
angiomyolipoma (2 papers, 2011 to 2023). A neoplasm with perivascular epithelioid cell differentiation often associated with tuberous sclerosis. "We found small mutations in TSC2 in 7 of 8 angiomyolipoma that were sequenced, and the single case that did not harbor a mutation was the VHL patient." (PMID 21949787, 2011).
asthma (2 papers, 2022 to 2023). "We identified a novel mechanism that lTSLP could promote inflammatory cytokines production by miR-223/VHL/HIF-1α pathway to upregulate aerobic glycolysis in airway epithelial cells in asthma." (PMID 35351157, 2022).
astrocytoma (2 papers, 2004 to 2023). "Seventeen genes (ABL, APC, APAF1, BRCA1, CSPG2, DAPK1, hMLH1, LKB1, PTEN, p14ARF, p15INK4b, p27KIP1, p57KIP2, RASSF1C, RB1, SURVIVIN, and VHL) displayed a uniformly unmethylated pattern in all the astrocytoma and non-astrocytoma tissues examined." (PMID 15367334, 2004).
Cachexia (2 papers, 2025 to 2026). Severe weight loss, wasting of muscle, loss of appetite, and general debility related to a chronic disease. "To ask how, mechanistically, OSRC-2 cells induce cachexia, we introduced a promiscuous biotin ligase (BirA) fused to an endoplasmic reticulum targeting signal (ER) into OSRC-2 cells and, as a control, 786-O VHL−/− ccRCC cells." (PMID 40964365, 2025). "To ask how, mechanistically, OSRC-2 cells induce cachexia, we introduced a promiscuous biotin ligase (BirA) fused to an endoplasmic reticulum targeting signal (ER) into OSRC-2 cells and, as a control, 786-O VHL−/− ccRCC cells; 786-O cells do not induce profound cachexia in mouse xenograft assays." (PMID 41315757, 2026).
carcinoids (2 papers, 2010 to 2021). "Here, we reported a case of multiple-site carcinoids in the lung and pancreas, and provided genetic evidence of potential association between the carcinoid and VHL gene mutation." (PMID 34923986, 2021). "For example, the heterozygous allelic deletions of VHL gene were demonstrated in the primary lung and metastatic brain carcinoids, which provide genetic evidence for potential role of VHL mutation in the pathogenesis of carcinoids." (PMID 34923986, 2021). "Although carcinoids have similar histological and cellular components to VHL-associated NET, it is not well known about relationships between VHL gene mutations and carcinoids development." (PMID 34923986, 2021). "However, there is no direct evidence suggesting a link between VHL gene mutations and carcinoids." (PMID 34923986, 2021).
chronic mountain sickness (2 papers, 2021 to 2024). A pathological condition resulting from chronic exposure to hypoxia at high altitude. "Furthermore, the DNMT inhibitor 5-azacytidine reduced chronic hypoxia-induced erythroid proliferation in the bone marrow of rats with chronic mountain sickness by suppressing VHL methylation and DNMTs expression." (PMID 34444030, 2021). "Chronic hypoxia was shown to significantly induce methylation at the CpG site in the VHL promoter, decreased VHL expression, and increased EPAS1 and EPO expression, leading to excessive erythrocytosis in a rat model of chronic mountain sickness." (PMID 34444030, 2021).
chronic myelogenous leukemia (2 papers, 2015 to 2024). "A screen of ~12,800 small molecules identified homoharringtonine (HHT), an FDA-approved drug for treating chronic myeloid leukemia, as a VHL-synthetic lethal agent in ccRCC." (PMID 26219258, 2015).
COVID-19 (2 papers, 2021 to 2022). A disease caused by infection with severe acute respiratory syndrome coronavirus 2. "MiR-21-5p and miR-22-3p, both upregulated in COVID-19 patients, target several genes involved in cell signaling, cell proliferation and angiogenesis (e.g., HIF1A, MYC, SP1, SMAD7, VHL)." (PMID 36032130, 2022).
cystic neoplasm (2 papers, 2024 to 2025). A benign or malignant neoplasm that contains a single or multiple cystic spaces. "Moreover, the VHL gene mutation was significantly more common in solid than in cystic tumors (p = 0.016)." (PMID 38666933, 2024). "The SCNs are cystic neoplasms that frequently occur in patients with VHL." (PMID 40918781, 2025).
diabetic retinopathy (2 papers, 2017 to 2024). "This state may lead to relatively decreased oxygen levels in the surrounding tissue, which can be speculated to have similar mechanisms to VHL expression and HIF-1α in diabetic retinopathy." (PMID 38732107, 2024).
DICER1 syndrome (2 papers, 2018 to 2020). "Of the ten patients who screened positive and carried pathogenic germline mutations, eight fulfilled clinical criteria for CPS including Li-Fraumeni syndrome (LFS, n = 3), DICER1 syndrome (n = 3), neurofibromatosis type 1 (NF1) (n = 1) and von Hippel-Lindau (VHL, n = 1) syndrome." (PMID 30455982, 2018).
endometriosis (2 papers, 2024 to 2025). The growth of functional endometrial tissue in anatomic sites outside the uterine body. "Thus, the striking disease-specific cooverexpression of TET3 and VHL would likely increase the specificity of Bc action and explain, at least in part, the high efficacy and low toxicity of Bc in our mouse endometriosis therapy studies." (PMID 39141428, 2024). "Curiously, we observed a positive correlation between TET3 expression and that of VHL in macrophages from MASH, NSCLC, and endometriosis, suggesting that TET3 may regulate VHL expression." (PMID 40794443, 2025).
Erythema (2 papers, 2011 to 2022). Redness of the skin, caused by hyperemia of the capillaries in the lower layers of the skin. "Splenomegaly and erythema are recognized signs of activation of the oxygen-VHL/HIF/EPO pathway, and they have been reported previously in transgenic mice overexpressing EPO." (PMID 21811636, 2011).